SOX4 (SRY-box transcription factor 4)
Diseases named in the same sentence as SOX4 in open-access papers (continued):
Sharing a sentence is not in itself a finding about the gene and the disease.
tumor (continued). "In addition, a significantly higher SOX4 mRNA expression was observed in tumor tissues than that in adjacent normal tissues from our cohort of 68 ESCC patients." (PMID 33854048, 2021). "High levels of SOX4 recovered miR-25 induced tumor inhibition." (PMID 33503899, 2021). "Therapeutic manipulation of SOX4 function could provide a novel strategy for cancer differentiation therapy, which would promote differentiation and inhibit cycling of tumor cells." (PMID 34584219, 2021). "Moreover, the anti-tumor property induced by THAP9-AS1 knockdown was significantly impaired due to miR-133b downregulation or SOX4 overexpression." (PMID 33854048, 2021). "SOX4 plays a role as a tumor suppressor or oncogene, depending on cellular context." (PMID 36618440, 2021). "Altered subcellular expression of MIF, SOX-4, β-catenin and E-cadherin may significantly contribute to tumor aggressiveness." (PMID 34157052, 2021). "When tumor samples were dichotomized into SOX4 high (top quartile) and low (bottom quartile) expressing subgroups, PI3K signaling was significantly upregulated in both the TCGA (p = 3.0 × 10−27) and METABRIC (p = 4.7 × 10−70) cohorts in SOX4 high expressing tumors." (PMID 33837205, 2021). "As the relevance of EMT to tumor growth is unclear it raises the question whether SOX4 affects tumor growth independently of regulating EMT." (PMID 34584219, 2021). "It is consistent with our findings confirming that SOX-4 may be responsible for regulation of the β-catenin signaling pathway, by influencing on β-catenin in tumor cells." (PMID 34157052, 2021). "Therapeutic manipulation of SOX4 may thus provide a novel approach to interfere with tumor propagating cells." (PMID 34584219, 2021). "In addition, SOX4 protein expression was lower in THAP9-AS1-depletion tumor tissues than that in the sh-NC group." (PMID 33854048, 2021). "IHC staining of SOX4 was performed on 42 tumor specimens and a TMA containing 133 samples." (PMID 34234874, 2021). "Next, we tested the role of SOX4 in the tumor drug resistance process." (PMID 34235197, 2021). "Considering the broad deregulation of SOX4 expression in cancer this may occur in other tumor types as well." (PMID 34584219, 2021). "Importantly, knockdown of SOX4 with siRNA in PC cells resulted in restricted tumor growth both in vitro and in mice." (PMID 34055896, 2021). "Furthermore, SOX4 expression was negatively associated with miR-133b expression, while positively correlated with THAP9-AS1 level in ESCC tumor tissues." (PMID 33854048, 2021). "Additionally, lncRNA UCA1 also can directly interact with miR-204 to reduce miR-204-mediated Sox4 degradation; thus, Sox4 can exert its biological role as a tumor-promoting protein to stimulate EC progression." (PMID 33936199, 2021). "Additionally, several other genes associated with poor prognosis in other cancers were upregulated in TAS but downregulated in tumor of BA vs WA patients including oncogene SOX4 and USP6." (PMID 34316327, 2021). "Accordingly, we supposed that MIF and SOX-4 factors may cooperate in acquiring invasive properties by tumor cells in prostate malignancies." (PMID 34157052, 2021). "In addition, SOX4 expression can be induced by inflammatory cytokines as TGFβ factors, typically present in the tumor microenvironment." (PMID 34945712, 2021). "Besides, the expression of circ_VANGL1 and SOX4 was downregulated, while miR-145-5p was upregulated in xenograft tumor tissues with doxorubicin treatment, circ_VANGL1 knockdown, and co-treatment of doxorubicin and circ_VANGL1 knockdown." (PMID 34258391, 2021). "The ‘core’ enrichment of fMaSC genes in control organoids (which are those genes that most strongly contribute to enrichment) consisted of a large proportion of the fMaSC geneset (118/300), suggesting that SOX4 has a strong impact on fMaSC genes in PyMT tumor organoids." (PMID 34584219, 2021). "The effects of tumor related genes (SOX4 and EDIL3) in IgAN need further clarification." (PMID 33936064, 2021).
tumor (continued). "Despite the evidence of miR-381-3p targeting Sox4 and Twist1, we cannot exclude other key genes that may contribute to the tumor-suppressive role of miR-381-3p." (PMID 34362391, 2021). "Bioinformatics and dual-luciferase reporter gene assays confirmed that lnc-42060 could act as a sponge for miR-204-5p, further regulating SOX4 expression activity and thus influencing tumor cell progression." (PMID 34235197, 2021). "We found that silencing HNF1A‐AS1 could suppress tumor growth, but this effect was reversed by overexpressing SOX4." (PMID 33448691, 2020). "A number of studies have verified that SOX4 controlled the TGF-β-induced epithelial-to-mesenchymal (EMT), a process closely associated with increases in invasive and migratory capacity of tumor cells." (PMID 32552762, 2020). "Moreover, the effect of SOX4 on tumor growth, metastasis, and resistance to chemotherapy was also studied in vivo by using bioluminescent imaging." (PMID 33005101, 2020). "We used RT-PCR to measure the expression of SOX4 in 10 tumor tissues and 10 normal tissues." (PMID 32090981, 2020). "In addition, knockdown of JPX was found to inhibit HeLa cell viability and tumor development via up-regulating the expression of miR-25-3p and inhibiting the expression of SOX4." (PMID 32943989, 2020). "SOX4 silencing could inhibit RB cell proliferation and invasion, suggesting it may serve as a tumor promoter in RB." (PMID 32127028, 2020). "This cluster also enriched some well‐known stemness markers such as Sox11, Sox4, Nestin, Ptprs, and Cdk4, suggesting that they may function as the TICs in the tumor." (PMID 33173731, 2020). "We observed enhanced expression of SOX4 levels in tumor tissues of PC samples." (PMID 32090981, 2020). "Numerous but conflicting reports indicate that Sox4 may act as either an oncogene or a tumor suppressor in a range of cancers." (PMID 30683134, 2019). "The SOX4 transcription factor is overexpressed in many types of human cancers and has been recognized as one of the 64 “cancer signature” genes, suggesting a key role in tumor progression." (PMID 30872583, 2019). "A role for SOX4 in tumor-induced angiogenesis remains unexplored and could be an essential component of its pro-tumorigenic effects." (PMID 30507376, 2018). "Here, there was also a modest effect on primary tumor growth, which may reflect better SOX4 knockdown in this experiment." (PMID 30507376, 2018). "Sox4 is a regulatory factor involved in tumorigenesis and tumor progression." (PMID 29490000, 2018). "Furthermore, in vivo assay results showed that propofol inhibited tumor growth; however, the inhibitory effect was abolished by Sox4 overexpression." (PMID 29490000, 2018). "A recurring theme is that SOX4 endows tumor cells with a more migratory and invasive phenotype." (PMID 30507376, 2018). "SOX4 mediated induction of ET-1 expression promotes tumor-induced angiogenesis in vitro." (PMID 30507376, 2018). "SOX4-ET-1 induced autocrine and paracrine signaling may thus affect multiple tumor-promoting processes." (PMID 30507376, 2018). "We provide the first evidence of a potential role for SOX4 in tumor-induced angiogenesis." (PMID 30507376, 2018). "We next examined whether depletion of SOX4 could inhibit ectopic sprouting induced by pro-angiogenic MDA-MB-231 tumor cells." (PMID 30507376, 2018). "SOX4 controls tumor-induced angiogenesis in vivo in a zebrafish tumor-xenograft model." (PMID 30507376, 2018). "Furthermore, the in vivo experiment revealed that propofol inhibited tumor weight via regulation of Sox4." (PMID 29490000, 2018). "However, the inhibitory effect of propofol on tumor formation was abolished by overexpression of Sox4." (PMID 29490000, 2018). "To determine whether SOX4 may regulate angiogenesis in vivo, we initially made use of a zebrafish tumor-xenograft model." (PMID 30507376, 2018). "But the associations between expression level of miR-204/SOX4 and patients' age, gender, tumor size, or tumor grade were not significant." (PMID 28133610, 2017).
tumor (continued). "Abnormal expression of SOX4 is related to malignant tumor transformation and cancer metastasis." (PMID 28841206, 2017). "This may also be in line with patient-based studies that have shown that elevated expression of SOX4 leads to better survival, decreased disease progression, and reduced tumor cell invasiveness in several different cancers." (PMID 28724437, 2017). "In addition, we established Sox4 knockout cells using CRIPSR/Cas9 approach and overexpressed LncSox4 in Sox4 knockout cells, followed by tumour initiation assays using gradient transplant model." (PMID 27553854, 2016). "The outcome of SOX4 activation depends on the cellular context and the tumor origin." (PMID 26578818, 2015). "The regulation of SOX4 affected the tumor proliferation via modulation of cell cycle." (PMID 26583330, 2015). "However, in contrast to the tumor-promoting role of SOX4, it can also act as a suppressor in some tumors, including bladder carcinoma, melanoma, and gallbladder cancer." (PMID 26578818, 2015). "All these demonstrated the role of SOX4 in tumor during EMT." (PMID 26578818, 2015). "MiR-204-5p may act as a tumor-suppressor by targeting IL-8, SOX4, USP47 and RAB22A genes and regulating the apoptosis, proliferation, invasion and tumor progression in GC." (PMID 26172537, 2015). "Also, Ki67 staining was significantly stronger in the tumor tissues formed by the SOX4-overexpressing CaSki cells than that formed by the control CaSki cells, suggesting that SOX4 enhanced tumor formation by promoting the proliferation of CC cells in vivo." (PMID 26583330, 2015). "The mechanism by which SOX4 is involved in tumor development and progression in many cancers remains unclear." (PMID 26555193, 2015). "However, SOX4’s mode of action in cancer is complicated as SOX4 can act either as an oncogene or a tumor suppressor." (PMID 25366337, 2014). "SOX4 has been proposed either as an oncogenor or a tumor suppressor." (PMID 25366337, 2014). "However, in cell line models of GBM, SOX4 seems to behave as a tumor suppressor, a discrepancy to the good prognosis offered by the high SOX4 expression." (PMID 25366337, 2014). "The clinical importance of SOX4 has gained increasing attention in recent years, with numerous reports suggesting that SOX4 may contribute to tumor progression." (PMID 23285187, 2012). "For one thing, SOX4 has been demonstrated as a tumor suppressor gene." (PMID 22510499, 2012). "In addition, SOX4 was expressed in 75.0% (102/136) tumor samples and was strongly expressed in 36 (26.5%), moderately expressed in 45 (33.1%), and weakly expressed in 21 (15.4%), and not expressed in 34 (25.0%) tumor samples." (PMID 22510499, 2012). "Furthermore, the IHC analysis demonstrated that the SOX4 protein found in the tumours was primarily of cancer cell origin." (PMID 19156145, 2009). "Consequently, SOX4 inhibits tumor ferroptosis through the reprogramming of fatty acid metabolism." (PMID 40399256, 2025). "Additionally, the SOX4 molecule is an important marker for IBC tumour-infiltrating antibody-secreting cells, which may mediate the high expression of collagen-related molecules by IBC tumour-infiltrating antibody-secreting cells to promote CAF proliferation." (PMID 40624675, 2025). "Similarly, SOX4 knockdown in PC-3 cells also inhibited the tumor growth in vivo." (PMID 39014441, 2024). "Target SOX4 may disrupt the interactions between tumor cells and CAFs." (PMID 39963655, 2024). "Moreover, this study also provides insight into the roles of SOX4 expression in immune cell infiltration, macrophage polarization, immune subtype, molecular subtype, and immunomodulators, as well as the tumor immune microenvironment (TIME)-related prognosis, in LIHC." (PMID 37958409, 2023).
tumor (continued). "Therefore, we used a stemness gene associated with tumor cell heterogeneity and SOX2, SOX4, SOX9, basal cell markers KRT5, KRT14, immune genes PD-Ll and epithelial-mesenchymal transition E-cadherin to study heterogeneous cell and malignant transformation mechanisms." (PMID 36056339, 2022). "Furthermore, we also explore whether the inhibition of Sox4 can affect the tumor-bearing mice mediated by IL-6 in vivo." (PMID 35513871, 2022). "Compared with SOX4-proficient tumoroids, tumoroids with SOX4 knockout contained more differentiated cells with luminal or basal gene expression patterns and lower levels of cell cycle genes and showed an impaired capacity for tumor growth and metastatic outgrowth." (PMID 35551634, 2022). "Moreover, the SOX-4 transcription factor may be involved in controlling many issues of tumor expansion in different types of cancer." (PMID 34157052, 2021). "While, it is unclear whether SOX4 activation of PI3K signaling is ligand-dependent, it has been documented that the TNBC tumor microenvironment is often enriched with TGFβ-family ligands produced by tumor cells and/or tumor-associated stromal and immune cells." (PMID 33837205, 2021). "Activation of SOX4 could affect many distinct biological processes, such as inhibition of apoptosis, enhanced cell migration and metastasis, and the induction and maintenance of tumor-initiating cells (TICs)." (PMID 33407675, 2021). "Future studies are warranted to confirm the differences in the extent of SOX4 gene expression between ATLL and PTCL-NOS, and to investigate whether there are any correlations between the intensity of SOX4 expression in tumor cells and the clinical prognosis of ATLL patients." (PMID 33923245, 2021). "Moreover, the study with gain- and loss-of-function have demonstrated that the SOX-4 may be responsible for enhanced β-catenin/TCF activity and the tumor cells proliferation of SW480 colon carcinoma cell lines." (PMID 34157052, 2021). "Paclitaxel may be a good therapeutic option if the expression level of SOX4 in the tumor is high." (PMID 33005101, 2020). "Furthermore, silenced circ-SOX4 also inhibited LUAD tumor growth." (PMID 31911754, 2020). "Importantly, the critical biological role of SOX4 in EMT has raised the question of whether SOX4 contributes to malignant tumor progression and metastasis." (PMID 30072631, 2018). "It should be noted that these experiments utilize the ‘aggressive’ MDA-MB-231 cell line where loss of SOX4 may not be sufficient to reduce primary tumor growth." (PMID 30507376, 2018). "Thus, our study may signify a potential connection between SOX4-mediated alterations in the tumor-microvasculature and the ability of cells to metastasize." (PMID 30507376, 2018). "SOX4-induced tumor angiogenesis may also contribute to metastatic dissemination." (PMID 30507376, 2018). "However, despite the similarity in phenotype that SOX4 confers in the various cell types, the overlap of transcriptional targets in the different studies has proven to be very limited suggesting that SOX4 has context-dependent effects on tumor development." (PMID 30507376, 2018). "Therefore, the primary mechanism through which SOX4 affects tumor initiation and progression may be deregulation of apoptosis." (PMID 26555193, 2015). "It is also possible that the tumor-suppressive roles of SOX4 mirror the effect TGF-β in these cell types, indicating that similar to TGF-β the outcome of SOX4 activation might be highly dependent on tumor stage and signals provided by the tumor microenvironment." (PMID 23301048, 2013). "Therefore, whether SOX4 may act as a tumor suppressor or an oncogene seems to be determined by the function of its interactors and the signal transduction it is involved in." (PMID 22510499, 2012). "However, the precise mechanism that SOX4 is involved in the tumorigensis and tumor progression of PGC remains unclear." (PMID 22510499, 2012).
tumor (continued). "Thus, SOX4 might exert different effects on tumor cells depending on the context and primary transformation mechanism; further studies are warranted to clarify this issue." (PMID 23285187, 2012). "Gene regulatory network analysis revealed that top regulators of Group 4 MB tumour cells include EOMES, SOX4, and SOX11." (PMID 41998565, 2026). "Key members such as SOX2, SOX4 and SOX9 notably influence the malignant progression of NSCLC by regulating processes including tumor stemness, EMT, cell proliferation, apoptosis, invasion, metastasis and drug resistance." (PMID 41268614, 2026). "Results showed that by interacting with tumor-suppressive gene miR-1253 as competing endogenous RNA (ceRNAs), AC093895.1 significantly upregulated the downstream gene SOX4 of AC093895.1/ miR-1253 axis, leading to tumor metastasis." (PMID 41633986, 2026). "For example, SOX2 sustains tumor stemness to promote chemotherapy resistance, SOX4 modulates EMT and angiogenesis and SOX9 collaborates with EGFR/KRAS signaling pathways to drive tumor invasion." (PMID 41268614, 2026). "The identification of transcription factors such as BPTF, SOX4, and KLF5 in ITGB8-high cells further implicates these factors in regulating tumor–stroma interactions and mediating the aggressive phenotype associated with a high MTSR." (PMID 41602481, 2026). "In BLC, NAT10 promotes tumor growth by upregulating key oncogenes such as B-cell CLL/lymphoma 9-like (BCL9L), SOX4, and AKT1 through ac4C modification." (PMID 41446042, 2025). "NAT10 remodeled the ac4C modification of the mRNAs of the oncogenic genes ATAD2, SOX4, and SNX5, which have been confirmed to play important roles in tumor metastasis and angiogenesis." (PMID 40301349, 2025). "Eight genes were differentially expressed at both the mRNA and protein levels, with ASCL1, EDNRB, INSM1, SOX11, SOX4, SOX8, and SIX1 showing reduced expression in tumor tissues, and CTNNB1 showing increased expression compared with para-cancer tissues." (PMID 40771813, 2025). "In BC, particularly TNBC, TGF-β pathway alterations involve multiple molecular players, including SOX4, MDM2, and circDISP3, ultimately promoting tumor growth and metastasis." (PMID 40804731, 2025). "In BLCA, NAT10 overexpression acetylates BCL9L, SOX4, and AKT1, promoting tumor invasion and metastasis." (PMID 38233930, 2024). "Regarding tumor proliferation, stable SOX4 overexpression, BMI1 silencing, SOX4 overexpression while silencing BMI1, or control H1299 cells were subcutaneously injected into BALB/c nude mice." (PMID 39349443, 2024). "We investigated the expression of SOX4 and CD44 in our tumor samples from xenograft mice treated with IBRD9 and in untreated tumors." (PMID 37739089, 2024). "Consistent with low WNT signaling in RevCSCs, BLM tumor stem cells had decreased expression of WNT/stemness-related genes compared to Min tumors such as Axin2, Id2, Sox4, Wnt6, Wnt10a, Id3, Prox1, and Id1." (PMID 38893159, 2024). "Subsequently, we used qPCR and western blot to determine the mRNA and protein levels of SOX4 in NSCLC tissues and adjacent normal tissues respectively, and also found that SOX4 was highly expressed in tumor tissues." (PMID 39349443, 2024). "For further verification, we performed the IHC assay on tumor sections from clinical patients of CRPC-Ad or NEPC and analyzed the staining intensity differences of SOX4." (PMID 39014441, 2024). "SOX4, an oncogenic transcription factor, has been shown to facilitate EMT and tumor progression in various cancers." (PMID 39551781, 2024). "To substantiate this classification, we examined the expression of hallmark canonical cell markers of cancer epithelial cells (EPCAM, SOX4, KRT7, KRT18, KRT19, KRT8) in C1 (normal epithelial cells) and the other clusters (tumour epithelial cells)." (PMID 38445456, 2024). "The correlations of SOX4 expression with the OS and DFS of patients across 21 tumor types based on the Kaplan–Meier Plotter are exhibited in forest plots, respectively." (PMID 37958409, 2023).